BAX (BCL2 associated X, apoptosis regulator)
Diseases named in the same sentence as BAX in open-access papers (continued):
Sharing a sentence is not in itself a finding about the gene and the disease.
lung carcinoma (56 papers, 2010 to 2025). "After all, the protein expression analysis after the MTX, ABL and the optimized MTX-ABL solid dispersion were tested against lung cancer cells for 24 hours using the Enzyme-Linked Immunosorbent Assay (ELISA) to assess the levels of BAX, BCL-2, TGF-β and FR-ɑ." (PMID 39821171, 2025). "O. gratissimum extract induced apoptosis in A549 lung cancer cells by activating caspases and modulating BAX and BCL-2 levels." (PMID 40218923, 2025). "Correlation analysis using the cancer tool suggests that FTH1 has a positive correlation with MAP1LC3B and pro-apoptotic protein BAX, whereas it is negatively correlated with the anti-apoptotic protein Bcl2 in lung carcinoma." (PMID 40538534, 2025). "The USP30 inhibitor auranofin demonstrates therapeutic potential by increasing BAX ubiquitination and mitochondrial localization, inducing BAX-dependent apoptosis in lung cancer cells." (PMID 40918504, 2025). "The combined effects of increased BAX levels and activated caspase-3 suggest a robust shift toward promoting cell death in the treated lung cancer cells." (PMID 40422202, 2025). "In lung cancer, the Bcl-2/BAX/caspase-3 signaling pathway was shown that it can enhance immunogenicity to inhibit the proliferation of lung cancer cells." (PMID 39074253, 2024). "According to the result of qRT-PCR, the expression of hTERT and BCL-2 genes decreased significantly, while the expression of BAX increased in the treated A549 lung cancer cells." (PMID 37664043, 2023). "enhanced chemopreventive potential against development of lung carcinogenesis by stimulating the apoptotic machinery.decreased BCL-2 expression and improved BAX protein expression in lung cancer cells." (PMID 36926328, 2023). "TheC.sappan ethanol extract inhibited cancer cell growth and arrested at G0/G1 phase of cell cycle, inducing apoptosis by increasing BAX/BCL-2 protein ratio in A549 lung cancer cell line." (PMID 36128561, 2022). "Betulinic acid has be demonstrated potent anti-cancer activity against PTX resistant H460 lung cancer cells by regulating BCL-2/BAX." (PMID 35477569, 2022). "Tetrandrine consequently reduces and increases the level of VEGF and BCL2-associated X protein (BAX), respectively, denoting the involvement of HIF-1α in the anti-angiogenic and apoptosis effects of tetrandrine in lung cancer." (PMID 34575983, 2021). "In the hepatocarcinoma cell lines SMMC7721 and HepG2 as well as lung carcinoma A427 cells, lupeol was shown to induce low expression of the antiapoptotic protein Bcl-2 and upregulate the proapoptotic protein BAX." (PMID 32571387, 2020). "Our results showed that after 10-HDA treatment of A549 human lung cancer cells, the expression level of antiapoptotic protein Bcl-2 decreased, and the expression of proapoptotic proteins BAX, cyto-c, caspase-3, and PARP increased in a time-dependent manner." (PMID 33376719, 2020). "When studying lung cancer cell A549, ginsenoside Rg3 induced apoptosis through upregulation of ROS formation and apoptosis protein caspase 3/9 and BAX." (PMID 31636686, 2019). "Cytotoxicity studies in four lung cancer cell lines were complemented with measurement of gene expression of apoptosis-related proteins Bcl-2, BAX and the pro-survival proteins NFκB-1 and COX-2, as well as quantification of caspase activity." (PMID 26861394, 2016).
lung carcinoma (continued). "This study demonstrates that s-cal14.1a induces cell death of lung cancer cell lines, gene expression levels of proteins involved in regulating and executing apoptosis reveal an interesting pattern for Bcl-2 and BAX mRNA levels." (PMID 26861394, 2016). "The presented tumour cell detection system is evaluated with nine H&E tissue core images of lung carcinoma and nine bright field immunohistochemistry tissue core images of lung carcinoma with a biomarker named BAX." (PMID 21386898, 2011). "Moreover, a comparative analysis revealed that the treatment with RJ and the combination of RJ and AVE resulted in decreased levels of the antiapoptotic protein BCL-2 relative to the pro-apoptotic protein BAX in lung cancer cells." (PMID 39838121, 2025). "Lung cancer cells generally escape apoptosis via BAX suppression and AKT/ERK overexpression." (PMID 38666017, 2024). "Also, immunoblot studies revealed quercetin, and curcumin-treated lung of mice significantly decreased BCL-2 expression and improved BAX protein expression in lung cancer cells." (PMID 36926328, 2023). "Regarding the anticancer effect of MET and SIL, in this research, we investigate the synergistic effect of co-delivery MET and SIL loaded in PEGylated niosome to enhance their bioavailability and evaluate their effects on the expression of hTERT, BCL-2, and BAX genes in NSCLC type lung cancer cells." (PMID 37664043, 2023). "That is, a few miRNAs can regulate MOAP1 and BAX, which may contribute to the apoptosis of lung cancer cells." (PMID 35269511, 2022). "In the NSCLC, the expression of BAX was highly showed in resistant lung cancer cells." (PMID 33390811, 2021). "In different types of lung cancer, we found BAX's expression was significant through meta-analysis." (PMID 33390811, 2021). "Moreover, it stimulated cell proliferation and increased total antioxidant capacity of A549 cells and triggered BCL2/BAX-mediated apoptosis, as well as necrosis and mitotic catastrophe, and inhibited the migratory potential of A-549 lung cancer cells." (PMID 31089377, 2019). "Here we studied the cytotoxic properties of s-cal14.1a in four lung cancer cell lines, we quantified the expression of genes involved in execution and regulation of apoptosis namely Bcl-2, BAX and the pro-survival proteins NFκB-1 and COX-2, we also analyzed caspase activity." (PMID 26861394, 2016). "The apoptotic profile of the lung cancer cells could be investigated using the measurement of the protein expression of the anti-apoptotic B-cell lymphoma-2 protein (BCL-2), and pro-apoptotic Bcl-2-associated protein x (BAX)." (PMID 39821171, 2025). "Further investigation of human lung cancer cell line A549 revealed that ginsenoside Rg3 could induce apoptosis by increasing ROS production and upregulate the expression of some apoptosis-related proteins, including caspase 3/9 and BAX." (PMID 40417000, 2025). "Finally, lncRNA XIST may be a useful biomarker regulating cisplatin resistance in lung cancer cells and further, we explored the BAX may effect tumor-infiltrating immune cells." (PMID 33390811, 2021). "The cytotoxicity assay and the ELISA to assess the levels of BAX, BCL-2, TGF-β and FR-ɑ after the MTX, ABL and the optimized MTX-ABL solid dispersion groups were tested against lung cancer cells, A549 cells, for 24 h." (PMID 39821171, 2025).
lung carcinoma (continued). "The S. platensis provided potential anti-proliferative effects on the A549 lung cancer cell line, such that significant up-regulations of the BRMS1 and BAX were reported." (PMID 41203700, 2025). "Echoing flow cytometry results, binding of pemetrexed to CD146 shRNA yielded the highest levels of cleaved PARP, cleaved caspase 3 and BAX, indicating that CD146 is resistant to pemetrexed mediated apoptosis in lung cancer brain metastases." (PMID 39872044, 2024). "IGFBP4 overexpression can inhibit tumor proliferation and induce apoptosis by increasing the expression level of the proapoptotic protein BAX and decreasing that of the antiapoptotic protein BCL2 in A549 lung cancer cells." (PMID 36164607, 2022). "In A549 lung cancer cells, we observed the upregulation of CDKN1A and BAX after re-expression of RASSF1A confirming its apoptotic functions." (PMID 29179447, 2017). "S. platensis has been shown to up-regulate the expression of BAX and down-regulate the expression of BCL2 in A549 lung cancer cells, which may contribute to its pro-apoptotic effect." (PMID 41203700, 2025). "Furthermore, the results of BAX expression experiments and hematoxylin–eosin staining showed that knockdown of LNC EBLN3P induced necrosis and apoptosis in lung cancer tissues." (PMID 36672460, 2023). "However, in lung cancer, IRX1 inhibits expression of the pro-apoptotic gene BAX, supporting a role of IRX factors in the (de)regulation of cell survival." (PMID 35328612, 2022). "Additionally, it has been reported that the PI3K/AKT pathway is involved in blocking apoptosis in lung cancer cell lines; p-AKT increases radioresistance by inhibiting the pro-apoptotic proteins BAD, BAX, and caspase-9." (PMID 34760374, 2021). "It should be noted that jorunnamycin A at nontoxic concentrations (0.05–0.5 μM) was previously reported to augment the level of BAX, a pro-apoptosis protein in human lung cancer cells; however, the overexpression of BAX was not indicated in CSC-enriched spheroids treated with jorunnamycin A." (PMID 34063628, 2021).
hepatocellular carcinoma (53 papers, 2010 to 2026). A malignant tumor that arises from hepatocytes. "Treatment of hepatocellular carcinoma with this extract increased the expression of BCL2-associated X protein (BAX) and a reduction in the expression of B-cell lymphoma 2 (BCL-2) protein, which played a role in promoting apoptosis induced by this extract." (PMID 41044220, 2025). "Treated hepatocellular carcinoma with an IC50 of GL extract (47.5 ug/ml) upregulates pro-apoptotic BAX and downregulates anti-apoptotic BCL2, which disrupts the BAX/BCL2 ratio, leading to activation of caspase 3 inside treated HepG2 cells." (PMID 37127764, 2023). "BMC Cancer 14: 938, 2014; and Gai X, Tu K, Li C, Roberts LR and Zheng X: Histone acetyltransferase PCAF accelerates apoptosis by repressing a GLI1/BCL2/BAX axis in hepatocellular carcinoma." (PMID 37449518, 2023). "For example, the localization of BAX at mitochondria or in the cytosol was reported to be clinically relevant in acute myeloid leukemia and hepatocellular carcinoma." (PMID 34754079, 2022). "In parallel, established hepatoma cell lines reflect only a small fraction of BAX/BAK regulation present in human cells." (PMID 32486514, 2020). "For example, cinobufagin was found to promote cell cycle arrest at the G2/M phase and apoptosis in hepatocellular carcinoma and esophageal squamous cell carcinoma by increasing the expression levels of pro-apoptotic p73 and BAX." (PMID 32933177, 2020). "It is well-known, that sorafenib is a strong inducer of apoptosis and exposure to hepatoma cells leads to BAX/BAK activation, at least in part through the BH3-only protein PUMA." (PMID 31921676, 2019). "Other EP300-associated factor, PCAF, accelerates apoptosis by repressing a GLI/BCL2/BAX axis in hepatocellular carcinoma." (PMID 28341962, 2017). "Lower expression of BAX is found in esophageal squamous cell carcinoma, hepatocellular carcinoma (HCC), breast cancer and ovarian cancer." (PMID 20226080, 2010). "According to a study on Cyclo(L-Leu-L-Pro) isolated from the sponge Callyspongia fistularis, the compound exhibited cytotoxic and apoptosis-inducing effects against human hepatocellular carcinoma HepG2 cells by significantly increasing the BAX/Bcl-2 protein expression ratio and activating caspase-3." (PMID 40867294, 2025). "Specifically, RAB31 might promote hepatocellular carcinoma progression by inhibiting cell apoptosis induced by the PI3K/AKT/Bcl‐2/BAX pathway." (PMID 29957874, 2018). "In HCC (hepatocellular carcinoma) liver cancer cells, baicalein increased BAX, decreased Bcl-2, and induced cleaved caspase-3, -9, and PARP." (PMID 36142874, 2022). "FAD induces caspase-dependent apoptosis through an increase in BAX and cleaved caspase-3 and a decrease in BCL2, RAB51, BRCA1, and MDC1 in hepatocellular carcinoma." (PMID 39765861, 2024). "PCAF can induce cell apoptosis by modulating the GLI1/BCL-2/BAX axis or by acetylating histone H4 and inactivating AKT signaling, which in turn suppresses hepatocellular carcinoma progression." (PMID 30833716, 2019). "Western blot analysis of PAPR, caspase-3, BAX, and Bcl2 also showed that CN30 induced apoptosis in hepatoma cells." (PMID 26393569, 2015). "In another study, mouse hepatoma cells treated with 30% ethanol extracts of CN in low or high doses showed a significant decrease in the expression of PCNA and p-AKT (proliferation markers) and increased expression of BAX, Bcl2, caspase-3, and PAPR (apoptosis markers)." (PMID 30806066, 2019).
hepatocellular carcinoma (continued). "Furthermore, salinomycin induces apoptosis in hepatocellular carcinoma cells (HepG2, SMMC-7721, and BEL-7402) by decreasing the level of the anti-apoptotic protein Bcl-2 and increasing the level of the pro-apoptotic protein BAX." (PMID 25531367, 2014). "In hepatocellular carcinoma (HCC) cells, ketoconazole downregulates the expression of COX2, thereby triggering PINK1-Parkin-mediated mitophagy to enhance apoptosis, downregulate BCL2, BCL-XL and MCL1 and upregulate BAX and BAK." (PMID 39013891, 2024). "Relative BAX/BAK localization was analyzed in tumor and corresponding non-tumor samples from 34 hepatocellular carcinoma (HCC) patients." (PMID 32486514, 2020).
glioma (51 papers, 2004 to 2025). A benign or malignant brain and spinal cord tumor that arises from glial cells (astrocytes, oligodendrocytes, ependymal cells). "It was observed that increased BAX expression resulted in a reduced survival rate of glioma cells (U251) and inhibited tumor growth in a xenograft animal model." (PMID 40286187, 2025). "determined that GST‐IL‐24 caused glioma cells to undergo autophagy by activating JNK1‐3, BAX, and inducing mitochondrial dysfunction." (PMID 40338095, 2025). "It is known that CASP3 activity and apoptosis in glioma cells are regulated by the balance between pro‐apoptotic BAX and anti‐apoptotic Bcl‐2 proteins." (PMID 40318008, 2025). "Our findings demonstrate that DET induces apoptosis in glioma cells by upregulating BAX and downregulating BCL2, consistent with previous studies in other malignancies." (PMID 39850823, 2024). "The western blot results showed that the protein level of BAX was up-regulated and that the protein level of Bcl-2 (an anti-apoptotic factor) was reduced by WZ-3146 treatment in glioma cell lines (U251 and LN229)." (PMID 38937742, 2024). "Several strategies, such as small molecule inhibitors, gene therapy, and immunotherapy, have been explored to modulate BAX and Bcl-2 expression and restore caspase-3 activity in glioma cells, with promising results in preclinical studies." (PMID 37185746, 2023). "The balance between pro-apoptotic BAX and anti-apoptotic Bcl-2 proteins is known to regulate caspase-3 activity and apoptosis in glioma cells." (PMID 37185746, 2023). "In conclusion, AKR1B1 regulated glioma cell proliferation through the involvement of p38 MAPK-induced BAX/Bcl-2/caspase-3 apoptosis signaling." (PMID 37185746, 2023). "This study aimed to investigate the regulatory role of Aldo-keto reductase family 1 member B1 (AKR1B1) in glioma cell proliferation through p38 MAPK activation to control Bcl-2/BAX/caspase-3 apoptosis signaling." (PMID 37185746, 2023). "The increase in BAX/Bcl‐2 ratio is thought to contribute to the sensitivity of glioma cells to anticancer therapy by activating the apoptotic cascade." (PMID 35703405, 2022). "Mechanistically, KLHDC8A regulated various functions in glioma by directly mediating Bcl2, BAX, p21, CDK2, MMP2 transcription and ERK and P38 MAPK activation." (PMID 32851798, 2020). "tBID activates BAX, an effector of apoptosis, and the cancer chemotherapy drug gemcitabine promotes BAX-dependent apoptosis of a glioma cell line via lysosomal ceramide accumulation and cathepsin D activation." (PMID 31474371, 2019). "Treatment of tumors with CNTFRα siRNA decreased the expression of p-AKT, BCL2 and Ki67, and increased the expression of cleaved Caspase 3 and BAX as observed in CNTRFα siRNA-transfected glioma in vitro." (PMID 28765641, 2017). "It has been reported earlier that downregulation of cathepsin B can induce apoptosis by suppressing Bcl2 expression and activating BAX accompanied by alternation in mitochondrial membrane potential in human glioma cells." (PMID 24667798, 2014). "Hypoxia affected glioma cell lines differently from adenocarcinoma cell lines: 8 proteins were increased in gliomas (BAX, caspase 7, HIF-1α, c-JUN, MEK1, PARP 1 cleaved, Src, and VEGFR2) and none in adenocarcinomas." (PMID 22276931, 2012).